STAT3 (signal transducer and activator of transcription 3)
Diseases named in the same sentence as STAT3 in open-access papers (continued):
Sharing a sentence is not in itself a finding about the gene and the disease.
glioblastoma (continued). "EGFR-SEPT14 fusions have previously been reported in glioblastoma, where they can activate STAT3 signaling and are sensitive to treatment with lapatinib or erlotinib." (PMID 37168365, 2023). "The interaction between CD109 and GP130 is known to increase STAT3 phosphorylation, thereby promoting stemness properties, tumorigenicity, and chemoresistance of glioblastoma stem cells and metastasis of lung adenocarcinomas." (PMID 37373457, 2023). "RCC2 promotes radio-resistance and propagation in glioblastoma by transcriptionally stimulating DNMT1 in a STAT3-dependent manner." (PMID 38008751, 2023). "Ibrutinib is a BMX inhibitor that crosses the blood-brain barrier and effectively inhibits the activation of glioblastoma stem cells STAT3." (PMID 36923251, 2023). "Aberrant STAT3 activation occurs in various carcinomas including glioblastoma, and STAT3 signaling pathway is recognized as a main mediator hub of aberrant cellular signaling regulatory networks and leads to poor prognosis." (PMID 37308741, 2023). "TXNIP acts as a tumor suppressor in glioblastoma by lowering STAT3 levels, which are increased by STAT3 inhibitors such as SS-4." (PMID 36366411, 2022). "We tested the impact of the core cysteines in the HGF PAN domain on STAT3 activation by following its phosphorylation in glioblastoma U-87 MG and HeLa cells." (PMID 35778602, 2022). "IL-6-mediated STAT3 activation enhanced cell migration and invasion in glioblastoma cells (U251, T98G, and U87MG)." (PMID 35368876, 2022). "Our previous study confirmed that RBM8A overexpression promoted glioblastoma growth and invasion through the Notch/STAT3 pathway." (PMID 35573726, 2022). "Emerging evidence revealed that curcumin suppresses STAT3 by reactivating the receptor activator of NF-κB (RANK) via demethylation through epigenetic modification in human glioblastoma cells." (PMID 36307808, 2022). "In summary, the results of the present study demonstrate that vitexin inhibits the proliferation and invasion and induces the apoptosis of glioblastoma U251 cells through suppressing the JAK/STAT3 signaling pathway." (PMID 35281458, 2022). "A recent report has stated that curcumin is able to hinder the aggressiveness of glioblastoma in vitro through the inhibition of the JAK/STAT3 pathway." (PMID 35328780, 2022). "ATO has been shown to inhibit glioblastoma cell proliferation, and inhibition of STAT3 by ATO as a viable therapy for glioblastoma multiforme was proposed." (PMID 35332210, 2022). "EZH2 binds and methylates STAT3 at K180 and enhances STAT3 tyrosine phosphorylation in glioblastoma, possibly by protecting it from dephosphorylation." (PMID 35795677, 2022). "STAT3 is required for tumor formation and the maintenance of self-renewal of glioblastoma-like stem cells, some of which expresses CD133 as a cancer stem cell marker." (PMID 35328780, 2022). "The activation of the hepatocyte growth factor/mesenchymal–epithelial transition (MET) pathway is implicated in the progression of glioblastoma, as it activates downstream signaling events including Ras/Raf/MAPK, STAT3, and PI3K/AKT/mTOR." (PMID 35743016, 2022). "Treatment with apigenin caused G2/M arrest in glioblastoma cells and decreased levels of Akt, mTOR, ERK, STAT3, and S6K proteins." (PMID 36193062, 2022). "Garcinol reduced glioblastoma tumor growth in an immunocompromised mouse model by reducing STAT3/STAT5A expression, enhancing the Bax/Bcl-XL apoptotic ratio, and downregulating the Ki-67 proliferation index, in vivo." (PMID 36193062, 2022). "In glioblastoma spheres, PPARγ ligands induce cell cycle arrest and apoptosis together with the inhibition on the STAT3 pathway." (PMID 36362294, 2022). "Collectively, our findings suggested that the PIKE-A/STAT3/FTO/SDHA axis is a promising target for anti-glioblastoma therapy." (PMID 36232604, 2022).
glioblastoma (continued). "The regulation of STAT3 is critical for Bcl-2-interaction cell death suppressor (BIS)-targeted cellular senescence in glioblastoma and ROS-induced senescence in lung fibroblasts." (PMID 36055997, 2022). "Glioblastoma stem cell-derived exosomes are enriched in phosphorylated signal transducer and activator of transcription 3 (STAT3) and skewed macrophages toward the M2 phenotype." (PMID 35600340, 2022). "A potential role for quercetin in the prevention and treatment of glioblastoma has been demonstrated as a suppressor of the STAT3 activation signaling pathway stimulated by IL-6." (PMID 35883021, 2022). "The same effect has been observed with Stt in BTIC glioblastoma cells; activation of STAT-3 induces upregulation of c-Myc, Cyclin D1 and Bcl-xL and protects against apoptosis to promote cell survival and proliferation." (PMID 35703345, 2022). "Curcumin is capable of significantly suppressing glioblastoma cell proliferation via modulation of the JAK/STAT3 pathway in both primary and recurrent human glioblastoma cell lines." (PMID 35328780, 2022). "It has been shown that quercetin can inhibit IL-6-induced glioblastoma cell growth and migration by regulating the STAT3 signalling pathway, which affects the expression of this protein in glioblastoma cells." (PMID 35971151, 2022). "The dual roles of STAT3 have also been identified in glioblastoma, in which STAT3 exerts both tumour-enhancing and tumour-suppressive effects depending on the genomic mutational profile." (PMID 35879773, 2022). "TXNIP expression increased in glioblastoma cells in response to SS-4 treatment, indicating that STAT3 tyrosine phosphorylation decreased TXNIP expression." (PMID 36366411, 2022). "Studies have now demonstrated that myeloid PD-L1 expression is induced by glioblastoma cell IL-6 cytokine secretion acting through STAT3." (PMID 36430641, 2022). "Among all STAT family members, STAT3 has the most comprehensive oncogenic activity and immune suppressive role in glioblastoma." (PMID 36193062, 2022). "Nevertheless, it is intriguing that molecular determinants (TGF-β, mTOR and STAT3) either in the glioblastoma cellular states and/or in the tumour microenvironment converge as regulators of NBCe1 activity." (PMID 36012235, 2022). "In conclusion, these findings offer new research directions to develop targeted therapies of STAT3-activated, autophagy-proficient tumors such as glioblastoma." (PMID 35053502, 2022). "TRIM8 regulates stemness in glioblastoma by activating STAT3 signaling and inhibiting the expression of PIAS3." (PMID 33923045, 2021). "Overall, our data suggest that β-elemene can inhibit the growth of glioblastoma cells through suppressing STAT3 signaling pathway, which is mainly regulated by ROS-mediated oxidative stress." (PMID 34257541, 2021). "The phosphorylation of signal transducer and activator of transcription protein 3 (STAT3) is up-regulated in glioblastoma (GBM) cells and is regulated by protein tyrosine phosphatase receptor type M (PTPRM)." (PMID 34225581, 2021). "Our result is also supported by another glioblastoma cohort in which STAT3-pSer727 levels were correlated with clinical outcome." (PMID 34732244, 2021). "Accordingly, the depletion of ferritin in glioblastoma stem-like cells affected their proliferation/cell cycle progression through the STAT3-Forkhead box protein M1(FOXM1) regulatory axis, revealing an iron-regulated CSC pathway." (PMID 34831207, 2021). "In this study, we found that β-elemene inhibited the growth of glioblastoma cells and induced apoptosis, accompanied by remarkable suppression of active STAT3 in a dose- and time-dependent manner." (PMID 34257541, 2021). "Although LINC00152 interacts with the transcription factor STAT3 mRNAs in both, myeloma and A172 glioblastoma cells, STAT3 only regulates LINC00152 expression in myeloma but not glioblastoma cells." (PMID 34531451, 2021).
glioblastoma (continued). "Overall, our findings implied that generation of ROS and suppression of STAT3 signaling pathway is critical for the apoptotic activity of β-elemene in glioblastoma cells." (PMID 34257541, 2021). "A study of the treatment of glioblastoma stem cells with Cardamonin found that the activation of STAT3 and downstream regulatory genes of STAT3 were inhibited by Cardamonin." (PMID 34539403, 2021). "Our data indicate that therapeutic targeting of CD109/STAT3 axis in combination with chemotherapy provides a relevant therapeutic approach to increase the effectiveness of glioblastoma treatment." (PMID 33986188, 2021). "For example, miR-21 represses TERT through a STAT3 transcription in glioblastoma cells and regulates TERT via the PTEN/ERK1/2 signaling pathway in colorectal cancer." (PMID 33802026, 2021). "A significant decrease in cell death time to 13 hours in all human glioblastoma cells analyzed in vitro was observed in this study using a combination of CT, a proteasome inhibitor drug, and a STAT3/5 inhibitor." (PMID 33544704, 2021). "ANXA2 was shown to regulate OSMR expression via STAT3 phosphorylation, resulting in the shift of glioblastoma cells towards a mesenchymal phenotype with a prominent proliferative capability." (PMID 33712571, 2021). "EZH2 can function independently of the other PRC2 subunits, methylating non-histone proteins such as STAT3, which results in enhanced STAT3 activation, as has been observed in glioblastoma." (PMID 33614973, 2021). "Constitutive activation or aberrant phosphorylation of STAT3 are often identified in many human cancer cells, including breast lung, prostate and glioblastoma." (PMID 34257541, 2021). "For instance, oleanolic acid can curb M2 polarization of macrophages and proliferation of tumor cells in glioblastomas via restraining STAT3 activation." (PMID 34604066, 2021). "ACT001 downregulates PD-L1 expression in glioblastoma cells through inhibition of the phosphorylation of the transcriptional regulator STAT3, leading to the inhibition of PD-L1 transcription." (PMID 34680439, 2021). "Nevertheless, studies about targeting EGFR and STAT3 in glioblastoma, non-small-cell lung cancer, and pancreatic cancer exhibit promising therapeutic efficacy." (PMID 34298665, 2021). "miR-411 suppressed the growth, migration, and invasion of glioblastoma cells via modulating signal transducer and activator of transcription 3 (STAT3)." (PMID 34606414, 2021). "Ang II/AGTR1 signaling pathway appeared more active in both glioblastoma cell lines displaying an enhanced phosphorylated status of STAT3 and MAPK in basal condition, which was further increased after Ang II short exposure." (PMID 34572782, 2021). "Another evidence showed that postoperative administration of resveratrol leads to suppressed tumor growth via apoptosis induction and STAT3 inactivation in advanced orthotopic glioblastoma rats, thus efficiently improving the prognosis." (PMID 34199460, 2021). "In the glioblastoma microenvironment, STAT3 is persistently activated in glioma cells, myeloid, and T cells and promotes tumor cell survival, proliferation, invasion, and immunosuppression." (PMID 34532286, 2021). "STAT3 has a key role in the expression of TERT in HCC, breast and glioblastoma where STAT3 expression levels correlated with TERT expression." (PMID 33802026, 2021). "Together these results demonstrate a vital role for CD109/STAT3 axis in the maintenance of glioblastoma cell stemness." (PMID 33986188, 2021). "The results showed that β-elemene induced STAT3 activation was blocked by an antioxidant, NAC, which is a ROS inhibitor, suggesting that β-elemene abrogated STAT3 activation via ROS-mediated oxidative damage and then induced apoptosis in glioblastoma cells." (PMID 34257541, 2021). "CA induced the glioblastoma cell apoptosis through inhibition of STAT3 and NF-κB activation and induction of apoptotic-related caspases pathways." (PMID 34831142, 2021).
glioblastoma (continued). "The OSM-mediated enhancement of migration and invasion of glioblastoma cells is significantly reduced after STAT3 inhibitor treatment, and the expression of gene markers related to neuron-mesenchymal transition is also restored." (PMID 34702277, 2021). "One such cytokine is transforming growth factor (TGF)-β, which is highly overexpressed in glioblastoma where it induces expression of the cytokine leukemia inhibitory factor (LIF) to consequently activate JAK/STAT3 to prevent differentiation of the GSCs." (PMID 33498872, 2021). "Although our data showed that STAT3 was contained in GC-derived EVs, a recent report demonstrated that STAT3 protein packaged in EVs was transferred from glioblastoma stem cells into macrophages to polarize them into the M2 phenotype." (PMID 33509150, 2021). "Activation of STAT3 is critical for tumour‐induced immune tolerance and avoidance in the glioblastoma microenvironment." (PMID 34449972, 2021). "Of note, a previous study has shown that EZH2 methylates STAT3 and enhances the Y705 phosphorylation and activity of STAT3 in glioblastoma cells." (PMID 33868295, 2021). "Targeting STAT3 along with agonists of intrinsic pathways of apoptosis has been suggested as a therapeutic approach for glioblastoma treatment." (PMID 34439380, 2021). "Tumorigenicity is preferentially augmented in glioblastoma via activation of STAT3 whereas EGFR contributes to survival of tumor cells." (PMID 33980886, 2021). "RRAD expression is reported to promote cell survival via activation of the EGFR/STAT3 signaling pathway and stimulate glioblastoma cell migration." (PMID 33980886, 2021). "Disturbed by STAT3 inhibitor, the healing rate of glioblastoma cells demonstrated a significant decline after 72 h of culture." (PMID 34702277, 2021). "The synergistic effect of cytokines TNF-α and IL-6 ascertained the belligerent nature of glioblastoma through activation of the NF-κB and STAT3 pathways." (PMID 34439380, 2021). "Recently, several reports showed STAT3 had vital roles in tumor progression; e.g., it was reported miR-519a enhanced chemosensitivity and promoted autophagy in glioblastoma by targeting the STAT3/Bcl2 signaling pathway." (PMID 33896365, 2021). "STAT3 was also identified as the direct target of many other tumor suppressors of glioblastoma, and STAT3 has also been indicated to be upregulated in glioblastoma." (PMID 34606414, 2021). "Members of the STAT3 pathway are also present in glioblastoma (GBM)-derived stem cells (GSCs)-derived exosomes (GDEs), functionally mediating the immune-suppressive switch." (PMID 34722637, 2021). "β-Elemene triggers ROS-dependent apoptosis in glioblastoma cells through suppressing STAT3 signaling pathway, it suppressed phosphorylation of STAT3, and subsequently down-regulated the activation of p-JAK2 and p-Src." (PMID 34257541, 2021). "Cancer-related inflammatory cytokine IL-6 regulates activation of STAT3 and is upregulated in glioblastoma." (PMID 34199460, 2021). "In brief, high CD109 expression is a biomarker of malignant glioblastomas, correlating with an increased activity of the STAT3 pathway and highly proliferating glioblastoma cells." (PMID 33986188, 2021). "A further increase in glioblastoma cell’s death was observed when CT, a selective STAT3 inhibitor, and other STAT3/5 inhibitor were combined reducing the cell death time to 11 hours." (PMID 33544704, 2021). "STAT3 activation and the transcription factor FOXM1, which is both downstream target gene and inductor of STAT3, thus constituting an activation feedback loop, are required to promote glioblastoma CSC self-renewal and tumorigenicity." (PMID 34831207, 2021). "Since STAT3 is known as a master regulator of MES transformation and glioblastoma stemness, we examined STAT3 signaling in GSCs under pioglitazone treatment." (PMID 32280134, 2020).
glioblastoma (continued). "Several studies have demonstrated that glioblastoma and medulloblastoma patients express higher levels of STAT3 as compared to healthy individuals." (PMID 32971907, 2020). "ODZ10117 inhibited migration and invasion and induced apoptotic cell death by targeting STAT3 in glioblastoma cells and patient-derived primary glioblastoma cells." (PMID 32183406, 2020). "This resulted in increased nuclear NFκB and STAT3 phosphorylation, two key transcription factors for immune activation that are also hyperactivated in glioblastoma." (PMID 33171886, 2020). "The postoperative administration of resveratrol results in a significant prognosis amelioration of rat-advanced orthotopic glioblastoma by reducing growth, inducting apoptosis, and suppressing STAT3 signaling." (PMID 32075265, 2020). "Recently, a novel STAT3 inhibitor, napabucasin, was shown to suppress proliferation of U87MG and LN229 glioblastoma cells highlighting the important role of STAT3 activation in proliferation of these cells." (PMID 32779712, 2020). "The acetylated derivative of tangeretin (5-AcTMF) had anticancer effects on human glioblastoma multiforme cells through blockade of Stat3 signaling." (PMID 32503228, 2020). "Curcumin blocks the survival and proliferation of cancer stem cell through a ROS-mediated inhibition of NFκB and STAT3 in glioblastoma." (PMID 32075265, 2020). "ObR-positive glioblastoma cells were responsive to leptin, which promoted cell growth and activated the STAT3/Akt cascade." (PMID 33316976, 2020). "In accordance with this, a recent study showed that napabucasin, a STAT3 inhibitor, suppressed the proliferation, invasion, and stemness of glioblastoma cells." (PMID 32102440, 2020). "Targeted inhibition of STAT3 signaling reverses immune tolerance and promotes cytotoxicity even in temozolomide-resistant glioblastoma." (PMID 33396284, 2020). "Studies have found that oleanolic acid, a triterpene compound, can inhibit the activation of STAT3 in macrophages and glioblastoma cells to suppress the M2 phenotype differentiation of macrophages and the proliferation of glioblastoma cells." (PMID 33224886, 2020). "According to the TCGA database, primary cell lines established from glioblastoma patients and GSCs, STAT3 is highly activated and its activation, tumor grade and patient survival rate are positively correlated." (PMID 32183406, 2020). "Ceacam1L promotes proliferation of glioblastoma cells by activating the STAT3 function, or Syndecan that suppresses T-cell activation in Sézary cells." (PMID 33333886, 2020). "We further analyzed the level of active STAT3 (phosphorylated at tyrosine 705 residue) in glioblastoma and primary glioblastoma cell lines." (PMID 32183406, 2020). "Vimentin staining for glioblastoma cells revealed an overall decreased invasion upon STAT3 knockout, as to be expected from our previous findings." (PMID 32967361, 2020). "ODZ10117 effectively inhibited tyrosine phosphorylation and nuclear translocation of STAT3, resulting in effective anti-tumor activity in both in vitro and in vivo xenograft models of glioblastoma and GSCs." (PMID 32183406, 2020). "The results of wound healing assay revealed that the migration of glioblastoma cells was regulated by STAT3, which was decreased in the presence of ODZ10117 compared to the vehicle-treated control group in primary glioblastoma cell line GBM14." (PMID 32183406, 2020). "Recently, arsenic trioxide has been shown to inhibit STAT3 activation, but it up-regulated autophagy in glioblastoma cells." (PMID 32971907, 2020). "For example, inhibitor OPB-51602 is showing promising effects against non-small cell lung carcinoma, and the STAT3 inhibitor napabucasin was shown to reduce both expression of stemness-related genes and sphere formation by glioblastoma cells." (PMID 32397392, 2020). "Glioblastoma is the most incurable type of cancer with few therapeutic options, and STAT3 is a promising therapeutic target for glioblastoma." (PMID 32183406, 2020).